STAT3 (signal transducer and activator of transcription 3)
Diseases named in the same sentence as STAT3 in open-access papers (continued):
Sharing a sentence is not in itself a finding about the gene and the disease.
tumor (continued). "Here, we used in silico analyses of multi-Omics data to map out the role of epigenetic and genetic alterations of STAT3/CDK2/4/6 in tumor immune infiltrations, immunotherapy response, and prognosis of cancer patients." (PMID 33668805, 2021). "Conversely, therapeutic targeting of STAT3 enhances anti-tumor T-cell cytotoxicity and reverses immune suppression by abrogating Tregs." (PMID 34944848, 2021). "Bazedoxifene is the inhibitor of IL-6/gp130 protein-protein interactions and our present studies find that Bazedoxifene can influence IL-6/gp130 interface and then inhibits IL-6/STAT3 signaling pathway in tumor and cardiovascular disease." (PMID 35118141, 2021). "In a carcinogen-driven model of NSCLC, genetic ablation of STAT3 in mice reduced urethane-induced tumorigenesis and increased anti-tumor inflammation by enhancing NK cell recruitment and activation." (PMID 34944848, 2021). "Tumor cells affect immune cells through the STAT3 signaling pathway and participate in the immune escape of tumor cells." (PMID 33688358, 2021). "In particular, high STAT3 expression is able to reduce dampen the expression of genes involved in glycolysis, allowing for tumor cells to grow in a hypoxic environment." (PMID 34829820, 2021). "STAT3 acts as an oncogenic factor by up-regulating pro-survival genes expression as well as metalloproteinases expression, thus favoring tumor invasion and metastases formation." (PMID 34262562, 2021). "MiR-6743-5p regulates the activity of STAT3 and promotes cell proliferation by directly targeting a gene associated with retinoid interferon-induced mortality-19 (GRIM-19), which serves as a tumour suppressor." (PMID 34425834, 2021). "Here, we expand on the tumor cell-extrinsic role of STAT3 signaling in the tumor microenvironment by modulating the activity of immune and stromal cells." (PMID 34944848, 2021). "Taken together, PLAGL2 plays a critical role in tumor apoptosis resistance through C‐MET/STAT3 activation." (PMID 34586726, 2021). "The so-called STAT3C mutant, a constitutively active form of STAT3, has been employed to confirm STAT3 as a primary tumor-cell intrinsic and microenvironmental target of silibinin." (PMID 34208282, 2021). "Studies have indicated that the hepatocyte-specific deletion of SHP2 led to the promotion of STAT3 signaling and thereby hepatic inflammation and tumor progression in mice." (PMID 34771643, 2021). "Our results here validated K685 at STAT3 is a crucial target to inhibit tumor cell growth/survival and elicit antitumor immune responses." (PMID 33491667, 2021). "JAK/STAT and STAT3 inhibition efficiently reverts astrocytes-related immunosuppression and delay tumor growth, indicating a central role of this pathway in controlling astrocytes immunomodulatory properties." (PMID 34690699, 2021). "The STAT3 role in leptin signaling is further attested by the fact that the inhibition of STAT3 had shown to promote cell cycle arrest, apoptosis and impede tumor invasion." (PMID 34588926, 2021). "Constitutively active STAT3 signaling in tumor cells has been shown to downregulate chemokine expression, including CCL5 and CXCL10, which are functionally responsible for T cell recruitment." (PMID 33777927, 2021). "Accumulating evidence shows that STAT3 carries tumor suppressor functions and the functions of STAT3 are dependent on co-existing biochemical defects or genetic background." (PMID 33670049, 2021). "Qing-Re-Huo-Xue (QRHX) formulae increases the expression of iNOS and decreases the expression of IL-6, TNF-α, and Arg-1 through the JAK2/STAT3 pathway, further reducing the numbers of TAMs and inhibiting tumor growth in lung cancer mouse model." (PMID 33748122, 2021). "Among the small molecules, BP-1-102 was formerly found to be a direct STAT3 inhibitor with reasonable in vivo tumour-inhibiting activity and commercial availability." (PMID 33440995, 2021).
tumor (continued). "Many studies show that inactivation of STAT3 pathway inhibits tumor cell proliferation, angiogenesis and metastasis." (PMID 34179090, 2021). "Linking tumor-NLRP3 induction of IL-6/STAT3 to immunosuppression, we assessed PMN-MDSCs in bone marrow and spleen from tumor-bearing mice treated with OLT1177." (PMID 34531850, 2021). "The results from the C57BL/6 tumor samples showed that STAT3 targeting combined with PD-1 blockade leads to a high CD8/CD4 ratio and a decreased percentage of Treg cells." (PMID 33936081, 2021). "Aberrant STAT3 activation triggers tumor progression through oncogenic gene expression in numerous human cancers, leading to promote tumor malignancy." (PMID 34900688, 2021). "IL-6/STAT3 signalling has been shown to play an important role in tumor progression in many solid tumor types by inducing epithelial-to-mesenchymal transition and angiogenesis." (PMID 33806019, 2021). "In this regard, NEAT1 has been shown to strengthen IL-6/STAT3 signaling and promote tumor growth and proliferation through nuclear trapping of mRNAs and proteins which acts as inhibitors of the IL-6/STAT3 signaling pathway." (PMID 34222014, 2021). "At the same time, TNF-α plays a biological role in tumor cells through the STAT3 signaling pathway, so the STAT3 signaling pathway is a bridge between inflammation and tumor." (PMID 33688358, 2021). "This contributes to the tumor growth, inhibition of apoptosis, and promotion of metastasis through STAT3 activation." (PMID 34941188, 2021). "STAT3 and NF-κB interact at multiple levels and promote inflammation, increasing tumor cell proliferation and survival as well as tumor angiogenesis and metastasis." (PMID 35008342, 2021). "While the specific mechanisms underlying the adoption of tumor-supporting TAM phenotypes are incompletely understood, activation of the STAT3 signaling pathway appears to play a predominant role." (PMID 34483843, 2021). "The combination of STAT3 inhibition with other immunotherapies, such as adoptive cell transfer, tumor vaccination, oncolytic virotherapy, and immune checkpoint inhibition, are rational." (PMID 33498872, 2021). "NETs can induce EMT of primary tumor cells in the early stage of metastasis and lead to the activation of inflammatory signaling pathways such as NF‐kB and STAT3, thereby enhancing the mobility and invasiveness of cancer cells and promoting metastatic growth." (PMID 34977870, 2021). "The medium-term results of a phase I clinical trial demonstrated that SRF388 inhibited STAT3 phosphorylation in 12 recruited tumor patients with mild adverse reactions." (PMID 35058928, 2021). "Radiation combined with pharmacological inhibition of STAT3 in the corresponding orthotopic murine xenografts led to decreased tumor size and prolonged survival, suggesting that STAT3 contributes to the baseline radioresistance of GSCs." (PMID 33498872, 2021). "Disruption of JAK2/STAT3/VEGF signalling by overexpression of PARK2 was shown to suppress OS tumour growth and angiogenesis in vivo and to induce OS apoptosis in vitro." (PMID 33382511, 2021). "In conclusion, in a TME rich in eATP, P2X7R activation in PSCs promotes IL-6 release that through STAT3 activation in cancer cells would promote tumor progression." (PMID 34440697, 2021). "As such, we analyzed the DNA-binding activity of STAT3 to the MMP2 promoter for tumor invasion, and the PD-L1 promoter for tumor metastasis." (PMID 33805840, 2021). "STAT3 has been demonstrated to be an important checkpoint that blocks anti-tumor immune responses in a variety of immune cells, especially CD8+ T cells." (PMID 33957948, 2021). "Interleukin-6 (IL-6)/Janus kinase (JAK)-2/STAT3 signaling has been widely studied in anti-tumor therapy and participates in the differentiation of osteoblasts." (PMID 33816498, 2021). "All these results suggest that the activation of STAT3 occurred simultaneously with elevated expression of CREPT in tumours." (PMID 33531691, 2021).
tumor (continued). "Although PTK6 was elucidated to be a tumor suppressor in normal epithelia, it promoted the azoxymethane-induced colon tumorigenesis in mouse models via activating STAT3." (PMID 34551797, 2021). "Studies have found that adiponectin can inhibit the proliferation of colon cancer cells induced by interleukin-6 (IL-6) by inhibiting the activation and phosphorylation of STAT3 and thus has an anti-tumor effect." (PMID 34485124, 2021). "Indicator transduction and activator of transcription 3 (STAT3) constitutively mediate tumor proliferation, progression and metastasis, and immunity in the TME." (PMID 33936081, 2021). "The change of BCL2 and PIM1 indicated the role of SPATS2-mediated p-STAT3 in HCC tumor growth, limitless replicative potential and resistance to apoptosis." (PMID 33391405, 2021). "Aberrant hyperactivation of IL‐6/STAT3 signaling occurs in many types of cancer and drives the proliferation, survival, invasiveness, and metastasis of tumor cells." (PMID 34375503, 2021). "Related studies have proven that MMP-2 and MMP-9 exist downstream of STAT3 and play an important role in tumours." (PMID 34222329, 2021). "Phosphorylated STAT3 produces anti-apoptotic, anti-proliferation, and anti-metastatic effects in tumor cells, and a STAT3 inhibitor exhibits anti-cancer activity through inhibition of STAT3 phosphorylation." (PMID 34638852, 2021). "A recent study reported that type I interferons enhance the activity of tumor-infiltrating cytotoxic T lymphocytes (CTL) by activating the STAT3/granzyme B pathway." (PMID 33406733, 2021). "Conversely, the disruption of constitutively activated STAT3 can promote cell apoptosis and suppress tumor-cell growth." (PMID 33909625, 2021). "Our study utilized qPCR, cytotoxicity and in vivo analysis of tumour and cancer‐associated fibroblasts (CAF) response to determine the synergy of Ref‐1 and STAT3 inhibitors." (PMID 33274592, 2021). "It is also well established in other cancers that p-STAT3 can play crucial roles in inducing cancer cell proliferation, tumor immunosuppression, angiogenesis, anti-apoptosis, and metastasis." (PMID 34170850, 2021). "Fibroblast growth factors (FGFs) released by CAFs are another key mechanism by which STAT3 modulates the crosstalk between CAFs and tumor cells." (PMID 34858425, 2021). "Suppressed tumor microenvironment-mediated angiogenesis by inhibiting the STAT3 signaling pathway in vascular endothelial cells." (PMID 35011278, 2021). "STAT1 is also a known tumor suppressor, whereas STAT3 is a well-known oncogene that is involved in the proliferation and survival of cancer cells." (PMID 33805945, 2021). "When STAT3 siRNA and IM were delivered together via LbL-GNP, there was a significant reduction in percentage tumor volume, tumor weight, and reduced STAT3 protein expression compared to either STAT3 siRNA or IM-packed LbL-GNP." (PMID 34360803, 2021). "Tumour proliferation and progression are promoted by activated STAT3 via gene expression regulation participating not only in cancer cell invasion and survival but also in immune escape and angiogenesis in the microenvironment of the tumour." (PMID 34291563, 2021). "Loss of TGF-β signaling and increased β1-integrin mechanosignaling in mice results in promoting tumor development by increasing matricellular fibrosis and tissue tension via STAT3 signaling." (PMID 34901028, 2021). "Locally or systemically treating tumor-bearing mice with PS-acet.-STAT3 peptide at low concentrations effectively blocked STAT3 in vivo, resulting in significant antitumor effects in 2 human xenograft models." (PMID 33491667, 2021).
tumor (continued). "Then, extracellular HMGB1 promotes the release of cytokines such as IL-6 and Tnf-α by activating MAPKs and Stat3 pathways, which stimulates tumor cells proliferation, angiogenesis, EMT, invasion, and metastasis." (PMID 35046917, 2021). "IL‐6/STAT3 activation by splice variant ΔNp63 results in the stabilization of hypoxia‐inducible factor 1α, the secretion of VEGF and angiogenesis in OS tumours." (PMID 33382511, 2021). "In a xenograft assay, DGG-100629 inhibited tumor growth by reducing the level of phosphorylated STAT3 and the expression of STAT3 target genes." (PMID 33859351, 2021). "Conversely, downregulation of STAT3 signaling inhibits tumor growth and induction of cell death in preclinical models." (PMID 33668421, 2021). "STAT3 modulates the expression of genes involved in tumor development and progression, including VEGF, c-Myc, cyclin D1 and survivin." (PMID 34360552, 2021). "The knockdown of GPR68 or the inhibition of IL-6/STAT3 pathway in MSCs suppress in situ tumor growth and prolong lifespan after cancer grafting." (PMID 34681692, 2021). "In pancreatic cancer, IL-6 not only promotes the occurrence and progression of tumours through JAK1/STAT3 but also activates reactive oxygen species through the ERK pathway." (PMID 34776511, 2021). "A statistical analysis showed that both levels of CREPT and STAT3 activation were higher in the tumour tissue than those in the paired adjacent non-tumour tissue." (PMID 33531691, 2021). "Overexpression of FGB protein resulting from an increased STAT3 expression is observed in patients with RCC, and it is associated with tumor progression and poor prognosis." (PMID 34769241, 2021). "Both Ref‐1 and STAT3 regulate downstream targets that play a role in tumour and stromal cell proliferation, response to hypoxia, and cytokine production." (PMID 33274592, 2021). "STAT3 is persistently activated in over 50% of NSCLC patients, and its increased expression is associated with poor tumor differentiation, advanced clinical stage, lymph node metastasis, and drug resistance." (PMID 34944848, 2021). "STAT3 has been described as a master transcriptional factor that drives tumor progression of multiple cancers via regulating the expression of key target genes such as VEGF, MMP and IL-6." (PMID 34930899, 2021). "Collectively, our study suggested that STAT3/CDK2/4/6 are important onco-immune signatures that play central roles in tumor immune invasion, poor prognoses and, immune therapy response." (PMID 33668805, 2021). "IL-6/STAT3 signaling was reported to stimulate tumor invasion, EMT and promote the survival of tumor cells after therapy to acquire treatment resistance." (PMID 34109109, 2021). "RPS6-KD reduced p-JAK2 and p-STAT3 and suppressed the tumor sphere formation, a characteristic of GSCs, of GBM cells in vitro." (PMID 35008473, 2021). "STAT3 facilitates to maintain the pluripotential phenotype of stem cell and tumor cell proliferation and invasion." (PMID 33750796, 2021). "Signal Transducer and Activator of Transcription 3 (STAT3) is a transcription factor and an oncogene product, which plays a pivotal role in tumor progression." (PMID 33753770, 2021). "Consistent with the subcutaneous tumours, the immunofluorescence results showed that the number of blood vessels in the liver tumours and the number of p-STAT3-positive blood vessels significantly decreased after bufalin treatment." (PMID 34496870, 2021). "STAT3 activity appears to mediate immune evasion by tumours, such as OS, by suppressing the tumour‐specific expression of pro‐inflammatory mediators." (PMID 33382511, 2021). "Potent, selective STAT3 inhibitors have been somewhat elusive to develop as many groups over time have attempted to target STAT3 both as an important target within the tumour itself as well as the role it plays in the tumour microenvironment." (PMID 33274592, 2021). "Blocking IL-6 signaling suppressed tumor formation and reduced STAT3 activation in Apcmin/+Ripk3-/- mice." (PMID 33996591, 2021).
tumor (continued). "It has been suggested that the transcription factor, STAT3, regulates the immunosuppressive activity and accumulation of MDSCs in the tumor microenvironment." (PMID 33717093, 2021). "Successful inhibition of STAT3 activation in NPC cells within tumor xenografts grown in nude mice well correlates with the inhibition of tumorigenic development of NPC cells in vivo." (PMID 34885950, 2021). "Regarding 14,15-EET, it was reported that 14,15-EET promoted tumour angiogenesis by stimulating tyrosine-protein kinase (Src) and activated transcription-3 (STAT-3)-dependent production of VEGF." (PMID 34590601, 2021). "For example, CAFs‐derived IL‐6 can activate the STAT3 pathway to promote EMT of tumor cells, thereby facilitating metastasis." (PMID 34977870, 2021). "Circ-STAT3 facilitated cell proliferation, invasion, migration, stemness, and tumor growth in HB by upregulating STAT3 and Gli2." (PMID 34116651, 2021). "Experimental studies suggested that inhibition of leptin or IL-6-JAK/STAT3 signaling in CRPC-cells enhances the anti-tumor NKCC via alteration of PD-L1/NKG2D-ligands levels." (PMID 34830209, 2021). "Overexpressed vascular endothelial growth factor A (VEGFA) and highly activated signal transducer and activator of transcription 3 (STAT3) contribute to the unrestricted tumor growth and vascularization of BRCA, especially TNBC." (PMID 34059068, 2021). "In tumor, the hyperactivation of STAT3 has been proved to suppress the maturation of bone marrow-derived DCs." (PMID 34429116, 2021). "STAT3, widely and aberrantly activated in many tumours, including CRC, is involved in cell growth, EMT and angiogenesis." (PMID 34936736, 2021). "The curcumin/siRNA-loaded liposomes inhibited tumor growth compared to either liposome-curcumin or STAT3 siRNA alone." (PMID 34683963, 2021). "IL-6 powerfully stimulating the activation of the JAK/STAT3 pathway to promote tumor proliferation, motility, and invasion." (PMID 33953676, 2021). "Under inflammatory conditions, NF-κB-induced IL-6, secreted from immune cells or tumor cells, can lead to cancer progression and metastasis via the IL-6/signal transducer and activator of transcription 3 (STAT3) signaling pathway." (PMID 33578830, 2021). "UCK2 has been reported to be highly expressed in HCC tumors It promotes tumor cell metastasis and invasion through the Stat3 pathway and can be used as an independent prognostic factor." (PMID 33869278, 2021). "Phosphorylated STAT3 dimerizes and translocates into the nucleus to induce the expression of genes with various tumor-promoting properties." (PMID 34869039, 2021). "Elevated STAT3 function is reported to prevent tumor cell apoptosis, while its inhibition suppresses proliferation and induces apoptosis in cancer cells." (PMID 34760885, 2021). "Mechanistically, SHP099 inhibited ERK1/2 phosphorylation and activated STAT3 phosphorylation in endothelial cells from culture and the tumor vasculature." (PMID 34102002, 2021). "Various tumor-derived factors have been shown to induce the expansion of myeloid-derived suppressor cells (MDSCs) through multiple pathways, including STAT3 or IL-4Rα-STAT6, resulting in the suppression of T cell function." (PMID 34572829, 2021). "It has been shown that IL-6 and activated STAT-3 lead to increased formation of tumor spheres, which initiated tumor growth in vivo." (PMID 34204596, 2021). "Persistent activation of STAT3 in tumor epithelial cells also promotes the secretion of pro-inflammatory cytokines, growth factors, and chemokines that facilitate the recruitment of immunosuppressive myeloid cells into tumors." (PMID 34944848, 2021). "Tumor cells derived GM-CSF induces FATP2 expression in MDSCs by STAT3 pathway activation, which confer the function of intratumoral PMN-MDSCs by the upregulation of arachidonic acid metabolism and the production of ROS." (PMID 34858835, 2021). "Tumor CM induced STAT3 activation, whereas its activation was canceled by S3I-201, a STAT3 inhibitor." (PMID 34226586, 2021).